INS (insulin)
Diseases named in the same sentence as INS in open-access papers (continued):
Sharing a sentence is not in itself a finding about the gene and the disease.
diabetes (continued). "Understanding the mechanisms underlying insulin action and the molecular interactions of ligands with the main human insulin receptor, hIR-B, is essential for developing more effective and safer therapeutic strategies for managing diabetes and related conditions." (PMID 40796375, 2025). "Diabetes mellitus (DM) is a chronic disease characterized by hyperglycemia, which is caused by the absolutely or relatively insufficient secretion and utilization of insulin." (PMID 40002886, 2025). "Diabetes mellitus (DM) is a syndrome characterized by hyperglycemia due to a deficiency in insulin secretion, action, or both." (PMID 39897826, 2025). "Insulin regulates antigen-mediated responses of bone marrow-derived mouse mast cells by enhancing IgE-mediated mast cell degranulation, with Fyn implicated in this downstream signaling pathway of insulin, which may be one of the mechanisms underlying the pathogenesis of diabetes mellitus." (PMID 40864777, 2025). "Finally, we used STZ as a model of insulin-deficient diabetes." (PMID 41373820, 2025). "Translating epidemiological risk to the bedside hinges on differentiating PDAC-DM from common type 2 diabetes using the timing of onset, weight trajectory, and insulin requirement." (PMID 41226286, 2025). "Therefore, analysis of the phenotypes of cells present in insulin-deficient islets of persons with T1D is of great importance for researching possible sources for the restoration of the β-cell mass in patients with diabetes and developing therapeutic approaches for the treatment of the disease." (PMID 39860066, 2025). "Also, another study demonstrated that targeted HRAS expression in pancreatic beta cells induces beta‐cell degeneration, leading to hyperglycemia, reduced plasma insulin levels, and diabetes, with associated structural damage to the islets of Langerhans and stress in the endoplasmic reticulum." (PMID 40823947, 2025). "Diabetes mellitus (DM) is a long-term and common condition caused by problems with insulin production, insulin action, or both, leading to high blood sugar levels." (PMID 40932957, 2025). "Diabetes mellitus (DM), a chronic metabolic disorder caused by the ineffective production of insulin by pancreas." (PMID 40378379, 2025). "These alterations were ameliorated by insulin treatment, suggesting that both insulin deficiency and hyperglycemia significantly influence keratinocyte differentiation and proliferation, potentially representing a primary mechanism underlying epidermal barrier impairment in patients with diabetes." (PMID 41377944, 2025). "Additionally, type 2 diabetes mellitus-related polymorphisms and single-nucleotide polymorphisms (SNPs) in genes regulating insulin signaling and inflammatory pathways may interact with these mutations, further elevating cancer susceptibility." (PMID 40989682, 2025). "Zinc deficiency may compromise pancreatic insulin synthesis and secretion, and diminish glucose uptake by peripheral tissues, thereby promoting the development of insulin resistance, a defining feature of diabetes mellitus." (PMID 40647294, 2025). "The author reported altered amino acid neurotransmitter levels in the fetal brain of pregnant Akita mice (a mode of diabetes caused by insulin dysfunction), indicating that there might be a link between diabetes triggered by insulin deficiency and congenital brain defects." (PMID 39446494, 2025). "Diabetes mellitus (DM) is a group of metabolic diseases caused by impaired insulin utilization (insulin resistance) or defective secretion (damage to β-cells), with elevated blood glucose levels as the main presenting symptom." (PMID 40106405, 2025). "Our findings revealed that vegetables such as parsley, kale, rocket, green and red chili, mushrooms, bitter gourd, and chicory are low in total carbohydrates and hexoses, suggesting that their inclusion in daily diets may improve insulin sensitivity and reduce the risk of diabetes." (PMID 41227672, 2025).
diabetes (continued). "Our research has unveiled S. deserti as a source of potential to effectively manage diabetes and its associated dyslipidemia by improving antioxidant status, recovery of the liver and kidney functions and presumably by increasing insulin secretion and sensitivity of peripheral tissues to insulin." (PMID 39995414, 2025). "Thus, it was found that the diets used to induce obesity were capable of causing changes in fasting blood glucose and insulin, which could result in the development of diabetes mellitus." (PMID 39408365, 2024). "Additionally, those products regulate blood sugar levels, lowering glucose and insulin levels in people with diabetes, and may also reduce the risk of developing diabetes." (PMID 38921431, 2024). "There are two major types of diabetes, together representing more than 95% of the total cases: type 1 diabetes, determined by an absolute insulin deficiency, and type 2 diabetes, characterized by insulin resistance, which is associated with a relative dysfunction in insulin production or function." (PMID 39768947, 2024). "Alzheimer’s disease (AD), also known as “type 3 diabetes mellitus (DM),” is associated with impaired insulin signaling observed in this condition." (PMID 38922352, 2024). "Additionally, the pancreas may become less efficient at producing insulin, further impairing glucose control and increasing the risk of diabetes." (PMID 39867544, 2024). "The insulin absorption rate from SC tissue depends on several factors, such as type of insulin formulation, concentration, added excipients, skin temperature, local blood flow, injection site, injection technique, lipohypertrophy, obesity, and comorbidities associated with diabetes." (PMID 37715091, 2024). "The distribution and frequency of these UCP2 gene polymorphisms may vary among different populations and can affect susceptibility to pancreas-related diseases, such as insulin secretion and type 2 diabetes mellitus, differently in various individuals and genders." (PMID 39707176, 2024). "Diabetes mellitus (DM) is a prevalent metabolic disorder resulting from a deficiency in insulin release, insulin action or a combination of both." (PMID 38739122, 2024). "Sedentary lifestyle leading to reduced peripheral insulin-mediated glucose uptake, which secondarily leads to glucose resistance caused by reduced sensitivity of muscle cells, implying that the risk of undiagnosed diabetes mellitus can be minimized by adopting sedentary lifestyle is avoided." (PMID 38713690, 2024). "Diabetes mellitus (DM) is a metabolic disease characterized by hyperglycemia caused by defects in insulin secretion, insulin action, or both." (PMID 38373910, 2024). "Diabetes mellitus (DM) is a serious endocrine and metabolic disease caused by impaired insulin secretion and insulin resistance." (PMID 39409089, 2024). "However, the positive impact of metformin was primarily observed in hormone-receptor-positive patients, suggesting potential improvement in prognosis associated with diabetes and insulin treatment in HER2-positive and hormone-receptor-positive breast cancer patients." (PMID 38254789, 2024). "Diabetes mellitus (DM) arises from insulin resistance and reduced insulin production and usage and has been linked to unhealthy lifestyle choices and obesity." (PMID 39155430, 2024). "While the association between diabetes and insulin has been well established as a fact and universally accepted as causal, there has been long-standing interest in characterizing the potential association between diabetes and various cytokines (including activin A)." (PMID 39280004, 2024). "Ghrelin and insulin therapies, while showing potential in regard to improving muscle function and protein synthesis, may pose risks, with insulin linked to poorer outcomes in heart failure (HF) patients with diabetes." (PMID 39795979, 2024).
diabetes (continued). "Diabetes mellitus (DM) is a metabolic disease caused by abnormalities in insulin secretion and function, leading to chronic hyperglycemia." (PMID 39347208, 2024). "An alternative strategy could involve incorporating glucagon or glucagon receptor agonists in conjunction with insulin and GLP-1 receptor agonists, targeting the complex interplay between these hormones and potentially offering benefits for both insulin-deficient diabetes and obesity management." (PMID 38579770, 2024). "Thus, reducing triglycerides could hold therapeutic promise in enhancing insulin sensitivity, an avenue yet to be recognized by the American Diabetes Association." (PMID 38611646, 2024). "Diabetes mellitus (DM) is a chronic disease that causes es excessive blood sugar levels caused by insulin secretion, insulin dysfunction, and/or both." (PMID 38611438, 2024). "Diabetes is a chronic and broad-spectrum metabolic disorder characterized by hyperglycemia, which occurs due to relative or absolute insulin deficiency or “insulin resistance” developed against the effect of insulin in peripheral tissues, affecting many organs and causing multisystemic involvement." (PMID 39051061, 2024). "Diabetes mellitus (DM) associates with decreased insulin secretion from pancreas, which results in elevated blood glucose." (PMID 38551943, 2024). "Diabetes mellitus (DM) is characterized by persistent hyperglycemia caused by defects in insulin secretion or function, classifying it as a chronic metabolic disease." (PMID 39290692, 2024). "Conversely, individuals with BMI < 25 kg/m2 who are not anticipated to have high insulin resistance may be less likely to benefit from this effect and may even face positive association with developing diabetes due to decreased insulin secretion caused by alcohol consumption." (PMID 39223288, 2024). "In addition, diabetes is one of the major risk factors for retinopathy, and vitamin D may protect the retina by improving insulin sensitivity and decreasing insulin resistance." (PMID 38895658, 2024). "Diabetes mellitus (DM) is caused by a relative or absolute deficiency of insulin secretion resulting in hyperglycaemia." (PMID 38796828, 2024). "For individuals with diabetes, medications such as metformin, sulfonylureas, DPP-4 inhibitors, GLP-1 receptor agonists, SGLT2 inhibitors, and insulin may be prescribed to manage blood sugar levels and reduce the risk of cardiovascular complications associated with diabetes." (PMID 38756312, 2024). "Pentacyclic triterpenoids decreased plasma glucose, HbA1c, enhanced plasma insulin, muscle and liver glycogen, and showed protective effects on the liver, eye and heart of diabetic rats, suggesting that they had the potential to prevent diabetes and associated complications." (PMID 39063310, 2024). "Experiments on Sprague-Dawley rats with streptozotocin-induced diabetes showed that the diabetes results in enhanced oxidation of lipid, glucose, and protein that is associated with reduced expression of eNOS, nNOS, and nitrotyrosine and can be effectively reduced by administration of insulin." (PMID 39769071, 2024). "Additionally, a chronic hyperglycemic condition is caused by insufficient insulin synthesis or by the inability of insulin to interact with cells, the prevalence of diabetes in the population aged 18 to 99 is predicted to increase from 8.4 % in 2017 to 9.9 % in 2045." (PMID 39286540, 2024). "There is evidence that zinc is essential for the proper processing of insulin by beta cells (formation of insulin hexamers), as well as storage and secretion; thus, zinc has a preventative effect on metabolic diseases associated with insulin resistance, including diabetes." (PMID 38247531, 2024). "Insulin, whether in the form of analogues or human, basal or mixed, was commonly reported (14 studies) to be associated with admission or ED presentation in older adults with diabetes." (PMID 38256662, 2024).
diabetes (continued). "Diabetes mellitus is defined by high blood glucose levels caused by either reduction in the number of insulin-producing cells (T1D), or an inability of our cells to respond adequately to insulin in combination with decreased numbers of insulin-producing cells (T2D)." (PMID 38702347, 2024). "Diabetes mellitus (DM), a chronic metabolic disease, is characterized by either a partial or total deficiency in insulin production (type 1 DM) or a periphery resistance to insulin’s action (type 2 DM)." (PMID 39408037, 2024). "Such ILPs could represent exciting exploitable scaffolds for future drug discovery in diabetes, as well as provide tools to allow for a better understanding of cell signaling pathways linked to insulin secretion and metabolism, which has potential biotechnology applications." (PMID 38535452, 2024). "Interestingly, 52.8% of these interactors could be linked with diabetes/β cell function/insulin signaling and/or puberty/pituitary function." (PMID 38775154, 2024). "Diabetes is associated with numerous complications, such as obesity; hyperglycemia; hypercholesterolemia; dyslipidemia; metabolic endotoxemia; intestinal barrier damage; insulin-secretion defects; increased oxidative stress; and low-grade, systemic, and chronic inflammation." (PMID 39125375, 2024). "Characterized by persistent hyperglycemia, diabetes mellitus (DM) is a common metabolic disorder caused by either the pancreas failing to produce enough insulin or the body becoming less responsive to insulin." (PMID 39683835, 2024). "Background and Aim: In patients with Diabetes Mellitus (DM), Enteral Nutrition (EN) is associated with less hyperglycemia and lower insulin requirements compared to Parenteral Nutrition (PN)." (PMID 39203739, 2024). "The American Diabetes Association recommends PwD and HCPs work together to optimize management goals and efforts, but the majority of insulin treatment optimization falls on self-management, where the patient must ensure they are taking the right amount of insulin at the right times every day." (PMID 38649812, 2024). "Diabetes mellitus (DM) is a group of common endocrine diseases caused by defective insulin secretion; insulin resistance leads to sustained high blood sugar levels, a condition known as hyperglycemia." (PMID 39204471, 2024). "Diabetes mellitus (DM) is a group of metabolic disorders caused by absolute or relative insufficiency of insulin secretion and (or) insulin utilization disorders, which is mainly characterized by hyperglycemia." (PMID 39839287, 2024). "Diabetes mellitus (DM) is characterized by impaired ability of producing or responding to insulin and has been reported to act as a risk factor of the progression of rotator cuff tendinopathy and tear." (PMID 38172847, 2024). "In addition, regular physical activity has a profound impact on diabetes management and it is associated with enhanced insulin sensitivity, pancreatic β-cell function, and improved whole body glucose metabolism, which directly promotes the improvement of glycemic control." (PMID 38981607, 2024). "Diabetes mellitus (DM) is defined as a group of metabolic disorders characterized by chronic hyperglycemia resulting from deficiencies in insulin secretion, insulin action, or both." (PMID 39279996, 2024). "Research from both in vitro and/or In vivo models suggests that inorganic nitrate/nitrite may serve as a substitute for endogenous nitric oxide (NO), improving glucose absorption and the signaling route for insulin while reducing insulin resistance and the problems associated with diabetes." (PMID 39493778, 2024). "That these mice are long‐lived and insulin‐sensitive conflicts with the notion that adipose tissue accumulation drives the health detriments associated with obesity (i.e., diabetes), and indicates that GH signaling may be necessary for the development of adverse effects linked to obesity." (PMID 38867381, 2024).
diabetes (continued). "Diabetes, characterized simply as hyperglycemia and/or acute-phase glucose intolerance, can arise as a consequence of insulin deficiency due to loss of pancreatic β-cells (type 1 diabetes mellitus) or impaired insulin secretion and insulin resistance (type 2 diabetes mellitus)." (PMID 37676263, 2024). "The observed associations between missed basal insulin doses and reduced glycemic control highlight a need for tools, such as smart insulin pens and other technologies, that provide precise injection data and empower patients and health care practitioners (HCPs) to improve the treatment of diabetes." (PMID 35775735, 2024). "Diabetes mellitus (DM) is a lifelong systemic disorder caused by impaired insulin metabolic mode of action resulting in impaired glucose homeostasis." (PMID 39424616, 2024). "Studies using techniques for the direct measurement of insulin action have demonstrated that insulin-stimulated glucose uptake varies several fold in apparently healthy individuals, and approximately one-third of these individuals are sufficiently IR to be at high risk of developing diabetes." (PMID 38672278, 2024). "Diabetes mellitus (DM) is a complex syndrome that is characterized by the loss of glucose metabolism homeostasis, which leads to chronic hyperglycemia due to insufficient insulin production by the pancreas or the ineffective use of insulin produced by the body." (PMID 39194853, 2024). "Peripheral insulin resistance and compromised insulin secretion from pancreatic β-cells are significant factors and pathogenic hallmarks of diabetes mellitus (DM)." (PMID 38778421, 2024). "Diabetes mellitus (DM) is a chronic metabolic disease characterized by high blood sugar levels resulting from a deficiency in the pancreas’ insulin production or a decreased sensitivity of cells to insulin." (PMID 38929670, 2024). "The term diabetes refers to different disorders of metabolism having multiple etiology but characterized by disturbances of carbohydrate, fat, and protein metabolism associated with chronic hyperglycemia resulting from defects in action or secretion of insulin." (PMID 38255850, 2024). "Type 1 diabetes mellitus (DM) is a chronic metabolic disease that leads to polyuria, polydipsia, and weight loss and is managed with insulin, exercise, and dietary planning." (PMID 39045940, 2024). "In addition, the gene has been associated with the type 1 diabetes mellitus phenotype, suggesting that it may impact insulin secretion regulation." (PMID 39415250, 2024). "Therefore, when considering increasing insulin secretion using gene therapy to reduce the risk of diabetes, it is important to carefully assess the potential damage that such interventions may cause to β-cells." (PMID 39596859, 2024). "While high levels of intracellular lipid content is often associated with metabolic pathologies such as type 2 diabetes mellitus and obesity, the accumulation of TG in athletes and endurance trainers has been shown to improve insulin sensitivity, a phenomenon known as the athlete's paradox." (PMID 37183563, 2024). "Diabetes mellitus (DM) is a multifactorial endocrine and metabolic disorder triggered by a combination of genetic predisposition and environmental influences, which disrupt insulin secretion and impair insulin sensitivity, ultimately resulting in multi-organ dysfunction and potential organ failure." (PMID 39559704, 2024). "In addition, we aimed to investigate whether a Diabetes Dietary Quality Index based on this questionnaire was related to metabolic risk factors, including measures of beta cell function and insulin sensitivity." (PMID 39458507, 2024). "It is well known that Diabetes Mellitus (DM) is associated with metabolic disorders and is characterized by the development of hyperglycemia due to insulin secretion deficiency." (PMID 38543163, 2024).